CCR2 (C-C motif chemokine receptor 2)
Diseases named in the same sentence as CCR2 in open-access papers (continued):
Sharing a sentence is not in itself a finding about the gene and the disease.
ischemia (22 papers, 2010 to 2025). A hypoperfusion of the BLOOD through an organ or tissue caused by a PATHOLOGIC CONSTRICTION or obstruction of its BLOOD VESSELS, or an absence of BLOOD CIRCULATION. "We found that C–C chemokine receptor type 2 (CCR2) deficiency, which blocks the migration of Ly6C+ macrophages from the bone marrow to the sites of injury, alleviated ischemia-induced AKI in mice." (PMID 30926787, 2019). "In the present study, propofol was shown to significantly downregulate the expression levels of CCL2 and CCR2 in the hippocampal tissues, indicating that propofol may decrease the inflammatory reactions caused by ischemia during reperfusion." (PMID 25009636, 2014). "This assumption is challenged by other studies demonstrating that deletion of the CCL2 receptor CCR2 contributes to an increased cerebral injury after ischemia." (PMID 39272984, 2024). "The number of CCR2+ monocytes peaks around day 3 post‐ischemia, whereas CX3CR1+ cells reach their peak much later, around 14–28 days after induction of ischemia." (PMID 33058417, 2020). "Western blot analysis showed that the protein expression levels of both Ly-6C and CCR2 in isolated whole splenocytes were rapidly increased at 4 h after ischemia onset, and their increases were almost completely suppressed by inhibition of CD147." (PMID 31666088, 2019). "This concept suggests that blockage of CCR2+ monocytes influx or recruitment during cardiac ischemia-reperfusion will be protective, while a strategy of depletion of resident macrophages (CCR2−) abolished that protection." (PMID 29375564, 2017). "The main outcome of this work is that the subacute administration of zinc increases the expression of CCL2, CCR2, and growth factors (FGF2 and IGF-1) as well as preventing the loss of memory in the rats after transient hypoxia-ischemia." (PMID 26355725, 2015). "Compared to normal mice, diabetic mice showed reduced MCP-1, IL-6, and CCR2 gene expression in the brain at 6 h post-ischemia." (PMID 24886035, 2014). "In the present study, the effects of preadministration of propofol on the expression levels of CCL2 and CCR2 in the hippocampus were investigated in rats with procerebral ischemia/reperfusion injury." (PMID 25009636, 2014). "Interestingly, CCR2 is the major receptor involved in brain infiltration of monocytes triggered by ischemia and plays a crucial role in their repairing functions." (PMID 35359933, 2022). "Similarly, quantitative PCR showed that mRNA expression of both Ly-6C and CCR2 in isolated whole splenocytes rapidly increased at 4 h after ischemia onset and was attenuated by inhibition of CD147." (PMID 31666088, 2019). "Firstly, although CCR2 deficiency inhibits the recruitment of inflammatory Ly6C+ macrophages and improves ischemia-induced AKI, it does not alleviate the subsequent CKD, because of the compensatory replenishment of intra-renal Ly6C− macrophages." (PMID 30926787, 2019). "Then, the upregulated Ccl2/Ccr2 by the combined zinc and selenium administration in the late phase of hypoxia-ischemia might be neuroprotective because they are known to decrease cell death and improve memory." (PMID 30258527, 2018). "Nearly all CCR2+ Mo/MΦ were located in the infarct area, consistent with an active involvement in the inflammatory processes occurring in the territory most affected by ischemia." (PMID 27814740, 2016). "We hypothesized that CCR2+Ly6Chi inflammatory monocytes are recruited in the early phase after ischemia and transdifferentiate into CX3CR1+Ly6Clo “repair” macrophages in the brain." (PMID 27814740, 2016). "In addition to CCR2 presentation on inflammatory cells, such as monocytes/macrophages and lymphocytes, it is also found in neurons and astrocytes, with reports showing increased CCR2 levels in the brain following ischemia and heat stroke." (PMID 33096826, 2020).
ischemia (continued). "In support of the harmful effect, experiments in CCR2 (−/−) mice have concluded that the absence of the CCL2 receptor (CCR2) prevents the cerebral injury following ischemia/reperfusion." (PMID 26355725, 2015). "MCP-1 may induce neural progenitor migration from the subventricular zone toward the damaged brain regions after focal ischemia, since expression of MCP-1 receptor CCR2 has been identified in the migrating neuroblasts." (PMID 23339567, 2013). "High expression of C-C motif chemokine receptor-2 (CCR2) on exosomes derived from MSCs could reduce the level of its ligand (CCL2) and suppress its effects to induce macrophage infiltration in mice with ischemia/reperfusion-induced AKI." (PMID 32082158, 2019).
neuroblastoma (19 papers, 2016 to 2026). Neuroblastoma (NB) is the most common solid, extracranial childhood tumor. "CCR2 was also found to be expressed in all 4 neuroblastoma cell lines examined, as well as a patient-derived xenograft tumor cells." (PMID 37964011, 2023). "CCR2 has been detected on T-cells, fibrocytes, natural killer cells, monocytes, and neuroblastoma cells, but is expressed significantly more by monocytes than other immune cells." (PMID 37964011, 2023). "A lower correlation was observed between CCL2 level and monocytes/macrophages, and PDC (IRF7) infiltration, suggesting the involvement of CCL2/CCR2 in APC recruitment by neuroblastoma tumors." (PMID 36923280, 2022). "CAR/CCR2 T cells displayed greater homing and tumor-killing in malignant pleural mesothelioma and neuroblastoma tumors in mice." (PMID 33381115, 2020). "Moreover, ubiquitous expression of CCR2 was identified on monocytes acquired from human patients with neuroblastoma." (PMID 37964011, 2023). "However, CAR T cells generated from neuroblastoma patients were found to have very low expression of the corresponding chemokine receptor, CCR2, despite expressing high levels of other chemokine receptors." (PMID 30459759, 2018). "Also, in xenograft tumor models of mesothelioma and neuroblastoma, the genetic introduction of CCR2 in T cells resulted in increased T cell infiltration in tumors secreting CCL2 and was associated with significantly increased anti-tumor activity." (PMID 27096098, 2016). "CAR-T cells overexpressing CCR2 has been found to enhance the migration and antitumor activity of CAR-T cells in xenograft neuroblastoma and mesothelioma models." (PMID 35443752, 2022). "Altogether, these results demonstrate the major involvement of the CCR2/CCL2 axis in the recruitment of APC by MYCN-nonamplified neuroblastoma." (PMID 36923280, 2022). "CCR2 (expressed by NKT cells) and CCL2 (expressed by a subset of MYCN non-amplified neuroblastoma cells) mediated homing of NKT cells to neuroblastoma was shown in subset of neuroblastoma patients." (PMID 31620124, 2019). "The investigators found that CARS coexpressed with the chemokine receptor CCR2b had improved homing and anti-tumor activity to CCL2-secreting neuroblastoma, compared to CCR2-negative CARs." (PMID 30736355, 2019). "Overall, our findings highlighted a major role for CCL2/CCR2 axis in monocytes, myeloid and plasmacytoid cells recruitment toward MYCN-nonamplified neuroblastoma, and suggest that the recruited myeloid DCs will further recruit T lymphocytes by means of CCL19 and CCL22." (PMID 36923280, 2022). "Overall, our findings highlight a major role for CCL2/CCR2 axis in monocytes, myeloid and plasmacytoid cells recruitment toward MYCN-nonamplified neuroblastoma, allowing further immune cell recruitment, and show that these tumors present a microenvironment that can favor DC responses." (PMID 36923280, 2022). "We observed that the migration of monocytes, myeloid and plasmacytoid DC induced by MYCN-nonamplified neuroblastoma supernatants was abrogated by the addition of anti-CCL2 antibodies, demonstrating the involvement of the CCR2/CCL2 axis in their recruitment by these tumors." (PMID 36923280, 2022). "Blocking experiments demonstrate that CCL2 is responsible for these CCR2-expressing cells recruitment by MYCN-nonamplified neuroblastoma, as already observed for the migration of CCR2-expressing NKT cells toward CCL2-expressing neuroblastoma." (PMID 36923280, 2022).
Cerebral ischemia (18 papers, 2008 to 2026). Restriction of arterial blood supply to the brain associated with insufficient oxygenation to support the metabolic requirements of the tissue. "Reports using Ccr2-deficient mice have also demonstrated that CCR2 signaling contributes to myocardial, renal, and cerebral ischemia-reperfusion injury." (PMID 33621212, 2021). "Therefore, CCL2 and CCR2 may be involved in the mechanisms underlying cerebral ischemia/reperfusion injury, and propofol may protect the brain through regulating the expression of CCL2 and CCR2." (PMID 25009636, 2014). "In this study, we used bioinformatics to identify and validate the differential expression of three target genes of miR-202-3p, Ptgs2, Tlr4, and Ccr2, in the cerebral ischemia penumbra of mice." (PMID 37563282, 2023). "Expression levels of CCL2 and CCR2 mRNA in the hippocampus were analyzed by qPCR following cerebral ischemia/reperfusion." (PMID 25009636, 2014). "The results of the present study indicated that there was a synchronous increase in the expression levels of CCL2 and CCR2 in cerebral ischemia/reperfusion injury and a synchronous decrease when propofol was injected into the rats prior to surgery." (PMID 25009636, 2014). "In conclusion, CCL2 and CCR2 are involved in the pathogenic mechanisms underlying cerebral ischemia/reperfusion injury in rats, and preadministration of propofol can suppress the expression of CCL2 and CCR2." (PMID 25009636, 2014). "The monocyte chemoattractant protein (MCP-1, CCL2) and its receptor CCR2 are known to be involved in the inflammatory response of the injured brain after cerebral ischemia." (PMID 25642168, 2014). "Protein expression levels of CCL2 and CCR2 in the hippocampus were analyzed by western blot analysis following cerebral ischemia/reperfusion." (PMID 25009636, 2014). "The aim of the present study was to determine the roles of the chemotactic factor, chemokine ligand 2 (CCL2), and its receptor, chemokine receptor type 2 (CCR2), in the hippocampus of rats with cerebral ischemia/reperfusion injury." (PMID 25009636, 2014). "Moreover, CCR2 is involved in inflammatory responses that damage the brain tissue after cerebral ischemia." (PMID 36566220, 2022). "Additionally, the inhibition of Ccr2 prevented neurobehavioral deficits in a cerebral ischemia model." (PMID 36499161, 2022). "miR-381-3p may play a pivotal role in hypoxic/ischemic encephalopathy, and CCR2 may be its direct target gene." (PMID 35246016, 2022). "Therefore, future research on the mechanisms underlying hypoxic-ischemic brain damage should investigate the effects of CCL2 and CCR2 using rats with cerebral ischemia/reperfusion." (PMID 25009636, 2014). "Importantly, the interaction of MCP-1 with its receptor CCR2 has been attributed a central role in experimental cardiac, renal and cerebral ischemia-reperfusion models." (PMID 21625615, 2011). "Furthermore, we found that baicalin could inhibit cerebral ischemia-induced activation of the NFκB/CCL2/CCR2 pathway via targeting NFκB activation and CCL2/CCR2 interaction." (PMID 36091824, 2022). "In cerebral ischemia models, CCL8 derived from microglial cells contributes to infarct progression by mediating CCR2/CCR5 CD8 T cell infiltration." (PMID 39475897, 2024). "In the acute phase of cerebral ischemia-reperfusion, the expression of CCL2/CCR2 is increased in the ischemic penumbra, which promotes neuroinflammation and enhances brain injury." (PMID 35408846, 2022). "Propofol may exhibit this neuroprotective effect in cerebral ischemia/reperfusion injury by regulating the expression levels of CCL2 and CCR2." (PMID 25009636, 2014). "Also, absence of Ccr2 reduced infarct sizes in a mouse model of cerebral ischemia/reperfusion injury, correlating with the current demonstration of reduced cortical cavity after TBI in Ccr2-deficient mice." (PMID 25153123, 2014).
experimental autoimmune encephalomyelitis (18 papers, 2007 to 2023). An autoimmune demyelinating disease of the central nervous system that is produced experimentally in animals by the injection of homogenized brain or spinal cord in Freund's adjuvant. "Here we identify a temporally regulated IL-23-dependent switch from CCR6 to CCR2 usage by developing Th17 cells that is critical for pathogenic Th17 cell-driven inflammation in experimental autoimmune encephalomyelitis (EAE)." (PMID 26511769, 2015). "JAK inhibition hindered the infiltration of C-C chemokine receptor type 2 (CCR2)-dependent Ly6Chi monocytes and monocyte-derived dendritic cells into the CNS in experimental autoimmune encephalomyelitis (EAE) mice." (PMID 38259497, 2023). "In another study, the very challenging conditional deletion of CD131 in a specific subpopulation through the myeloid lineage CCR2+Ly6Chi was achieved and used to study experimental autoimmune encephalomyelitis (EAE)." (PMID 35008482, 2021). "Depleting CCR2+ monocytes in marmoset monkeys with experimental autoimmune encephalomyelitis using a novel humanized CCR2 targeting antibody translates into significantly less cortical demyelination and disease severity." (PMID 28386765, 2017). "In mice with experimental autoimmune encephalomyelitis, CCR2 was critical for efficient intrathecal accumulation and localization of Ly6Chi/CCR2hi monocytes." (PMID 21060874, 2010). "A recent study reported that IL-23 drives switch of surface signature from CCR6 to CCR2 which defines GM-CSF/IFNγ-producing inflammatory Th17 cells and that CCR2 drives these cells to the central nervous system (CNS) in experimental autoimmune encephalomyelitis (EAE)." (PMID 29259681, 2016). "We therefore tested the effect of MK0812 in mouse experimental autoimmune encephalomyelitis (EAE), a model in which CCR2+Ly6Chi monocytes play a crucial role in disease pathology." (PMID 19906300, 2009). "In this study, we characterize the regional, temporal and cellular expression of CCR1, CCR2 and CCR5 mRNA in the spinal cord of rats with myelin oligodendrocyte glycoprotein-induced experimental autoimmune encephalomyelitis (MOG-EAE)." (PMID 17484785, 2007). "Mice devoid of CCR2 show a marked reduction in monocyte extravasation whereas mice lacking CCL2 show attenuated demyelination during experimental autoimmune encephalomyelitis." (PMID 37893243, 2023). "Interestingly, CD4+ T cells needed to be primed by NLRP3 inflammasome-sufficient antigen-presenting cells to upregulate chemotactic proteins such as osteopontin, CCR2, and CXCR6 in experimental autoimmune encephalomyelitis (EAE)." (PMID 36766797, 2023). "Classical inflammatory CD14++CD16− monocytes, with high CD192 (also known as CCR2, a chemokine receptor that binds monocyte chemoattractant proteins, MCP-1) expression, due to interleukin-1β (IL-1β) secretion cross the blood–CNS barrier before experimental autoimmune encephalomyelitis onset." (PMID 37893243, 2023). "As a positive control, we crossed Siglechdtr with Ccr2RFP mice to label CCR2+ cells with red fluorescent protein (RFP) and confirmed that a large number of RFP+ cells infiltrated the spinal cord of Siglechdtr/dtr:Ccr2RFP/+ mice after induction of experimental autoimmune encephalomyelitis (EAE)." (PMID 32959911, 2020). "Although qualitative in nature, this data reflects recent observations made following experimental autoimmune encephalomyelitis in CCR2-RFP/CX3CR1-GFP mice, where unlike the highly ramified microglia, MDMs were elongated or spindle shaped, smaller and rarely had processes." (PMID 30376851, 2018).
parasitemia (18 papers, 2007 to 2025). "Like IAV, parasite infection induced pre-cDC recruitment to lungs but, in contrast to infection with the virus, this was unaffected by loss of CCR2 in cDC precursors." (PMID 34739343, 2021). "Parasitemia, clinical score, and loss of body weight were similar in CCR2 KO mice compared to CCR2 WT mice, both during infection and during/after antimalarial treatment." (PMID 33664739, 2020). "Other studies using the Colombian strain of T. cruzi have shown that CCR2-deficiency leads to increase in parasitemia." (PMID 31356587, 2019). "The lack of splenic myelopoiesis resulted in a significantly delayed resolution of parasitemia in CCR2 deficient mice when compared to the control group." (PMID 23762028, 2013). "From this, we identified 26 common DEGs downregulated in Tr1 cells from both parasitic diseases, including Ccr7, Tcf7, and Bcl6, as well as 29 upregulated DEGs, including Il10, Havcr2, Prdm1, Ccr2, Ccr5, Maf, and Lag3." (PMID 37917177, 2023). "Functional and constitutive CCR2 can be expressed in B cells, and in the case of parasitic infection, B‐cell growth was enhanced in CCR2–/– mice." (PMID 35875970, 2022). "Together, the results revealed a dramatic expansion of CD14+CD16− monocytes after parasite infection in vitro with a concomitant increase of CD64 expression but a strong decrease of CCR2." (PMID 31316920, 2019). "Remarkably, after in vitro parasite infection, expression of the chemokine receptor CCR2 was severely impaired in monocytes from both, individuals with chronic toxoplasmosis and seronegative controls." (PMID 31316920, 2019). "Although the cytokine profile indeed argues for a pro-inflammatory function, it is interesting to note that CCR2 levels and positivity were strongly decreased in response to parasite infection in vitro." (PMID 31316920, 2019). "Elevated numbers of CD14hi monocytes which co-express the chemokine receptors CCR2 and CX3CR1 have been associated with lower parasitemia and increased ADCI activity in P. falciparum-infected individuals with uncomplicated malaria." (PMID 26149666, 2015). "Our results suggest this is a causal association as circulating MO expressing CCR2, CX3CR1, CD56, mTNF-α and mIFN-γ are not only associated with lower parasitemias but also are associated with strong ADCI activity." (PMID 19851453, 2009). "Studies carried out with CCR2−/− mice clearly demonstrated that this receptor exhibits functions as a major mediator of macrophage recruitment and trafficking in host defense to bacterial and parasitic infections." (PMID 35360222, 2021). "Consistent with the lack of splenic myelopoiesis in the absence of CCR2 we observed a significant persistence of parasitemia in malaria infected CCR2-deficient hosts." (PMID 23762028, 2013). "Recruitment of myeloid progenitors and more advanced monocytic precursors including “inflammatory monocytes” from the BM enables a more efficient removal of parasite-infected erythrocytes which is inline with the observation of prolonged acute parasitemia in Ccr2-null hosts." (PMID 23762028, 2013). "However, although Tip-DCs and TNF levels were reduced in CCR2 KO mice, control of parasitemia was unaffected." (PMID 20714353, 2010). "Although TNF and IFN-γ are involved in the control of parasitemia during T. brucei infection, parasitemia in WT and CCR2 KO mice was similar indicating that reduced production of TNF and IFN-γ in CCR2 KO mice was still sufficient for efficient parasite control (not shown)." (PMID 20714353, 2010). "Furthermore, we have shown that patients with high numbers of CD14hi CCR2+CX3CR1+ MO had lower parasitemias than patients with low numbers of CD14hi CCR2+CX3CR1+ MO." (PMID 19851453, 2009). "Similar peak parasitemia was observed on day 7 post-infection in both groups of mice [Single parasites (32.2% ± 9.3 vs. 29.4% ± 5.4., C57BL/6 vs. CCR2-/-, n.s.), Multiple parasites (3.7% ± 1.9 vs. 2.9% ± 1.6., C57BL/6 vs. CCR2-/-, n.s.)]." (PMID 39452729, 2024).